IFIT1 (interferon induced protein with tetratricopeptide repeats 1)
Diseases named in the same sentence as IFIT1 in open-access papers (continued):
Sharing a sentence is not in itself a finding about the gene and the disease.
HCMV infection (7 papers, 2019 to 2025). "Here, the authors show that HCMV infection increases citrullination of host and virus proteins to promote infection and that citrullinated interferon-inducible protein IFIT1 is impaired in RNA binding, as a potential mechanism of evasion." (PMID 34162877, 2021). "As expected, overexpression of IFIT1 reduced viral titer by >2-log compared to AdVLacZ control, indicating that IFIT1 strongly impairs HCMV infection in HFFs." (PMID 34162877, 2021). "Studies of HCMV infection in the presence of cycloheximide (CHX) have shown upregulation of IFIT1 (IFI56), IFIT2 (ISG54), IFIT3 (cig49, ISG60), MxA (the protein produced from the Mx1 gene) and ISG15." (PMID 30871003, 2019). "In the context of the HCMV infection, Ashley and colleagues demonstrated that the promoters of several core IRGs, including IFIT1, IFIT3, MX1, and ISG15, are transcriptionally induced by the activation of the transcription factor IRF3 and therefore function independent of the IFN responses." (PMID 36552792, 2022). "Given the emerging evidence supporting an antiviral role of IFIT1 against HCMV infection, we asked whether ectopic expression of IFIT1 would curb viral spread in our system." (PMID 34162877, 2021). "Several ISGs, including IFIT1, IFIT2, IFIT3, Mx1, Mx2, CXCL10 and ISG15 were found to be upregulated transcriptionally following HCMV infection independently of type I IFN-initiated JAK-STAT signaling, but dependent on intact IRF3 signaling." (PMID 30871003, 2019). "Previously, we demonstrated that during HCMV infection several members of the interferon (IFN)-induced protein with tetratricopeptide repeat (IFIT) family were heavily citrullinated, and that IFIT1 lost its restriction factor activity when citrullinated in vitro." (PMID 38055760, 2023). "To gain further insight into the role of these genes during HCMV infection, we measured virus production in HCMV-infected HFFs after siRNA-mediated depletion of Mx1 or IFIT1—the latter having been shown to exert antiviral activity against HCMV only in fetal astrocytes upon lentiviral overexpression." (PMID 34162877, 2021). "Induction of the IFN-independent ISG viperin during HCMV infection is known to be induced by either IRF3 or IRF1, binding directly to its promoter, and this may also be the mechanism of IFIT1, IFIT2, IFIT3, CXCL10, Mx1, Mx2 and ISG15 upregulation." (PMID 30871003, 2019). "In contrast, upon infection with AD169ΔIE1, we observed a 6.3-, 3.5-, and 2.2-fold decrease in IFIT1, Mx1, and IFIT3 enrichment, respectively, which further supports the crucial role played by the IE1 protein in PAD-mediated citrullination during HCMV infection." (PMID 34162877, 2021).
pancreatic cancer (7 papers, 2015 to 2025). "The capacity of IFIT1 to promote EMT in pancreatic cancer cell lines is thought to be caused by the Wnt/β-catenin pathway, which is upregulated during IFIT1 overexpression." (PMID 36851555, 2023). "Upregulation of IFIT1 expression has been found in pancreatic cancer and was reported to correlate with patients’ poorer overall survival." (PMID 40564154, 2025). "Knockdown of IFIT1 in pancreatic cancer cells decreased their proliferation, migration and invasion." (PMID 40564154, 2025). "Biological and oncogenic functions of other IFIT family members have been demonstrated, and IFIT1 increased pancreatic cancer cell proliferation, migration, and invasion by activating the Wnt/β-catenin pathway." (PMID 38273364, 2024). "Analysis of IFIT1 expression in pancreatic cancer cell samples showed that that it was overexpressed in relation to normal pancreatic cell samples." (PMID 36851555, 2023). "When IFIT1 was tested in pancreatic cancer cell lines, the cells overexpressing IFIT1 exhibited a greater capacity for invasion than IFIT1 knockout cells." (PMID 36851555, 2023). "Along with their role in OSCC, IFIT1 and IFIT3 have recently been shown to contribute to the progression of pancreatic cancer, which exhibits a 5-year overall survival rate of about 7%." (PMID 36851555, 2023). "KLF7 promotes pancreatic cancer growth and metastasis by upregulating ISGs that include IFI6, interferon-induced protein with tetratricopeptide repeats 1 (IFIT1) and IFIT328." (PMID 34650128, 2021). "Similar to IFIT1, IFIT3 also contributes to the progression of pancreatic cancer." (PMID 36851555, 2023). "Unlike IFIT1, IFIT3 promotes metastasis in pancreatic cancer cells by inhibiting the proapoptotic effects of IFIT2 and by upregulating the secretion of vascular endothelial growth factor (VEGF) and IL-6." (PMID 36851555, 2023). "In addition, IFIT1 was detectable in normal pancreas and in 9 out of 11 cancer samples, while IFIT2 and IFIT5 could not be found in either normal pancreas or pancreatic cancer samples." (PMID 25650658, 2015).
colorectal cancer (6 papers, 2017 to 2025). A primary or metastatic malignant neoplasm that affects the colon or rectum. "Inhibits apoptosis in colorectal cancer cells via negative regulation of host defense mediators, (IFIT1/2)." (PMID 40028182, 2025). "The β-catenin/TCF2 complex and down regulation of IFIT1/2 is commonly seen in colorectal cancer compared to normal tissue." (PMID 40028182, 2025). "In addition, m6A-modified IFIT1 was found to induce PDL1 upregulation in an independent colorectal cancer model." (PMID 38898490, 2024). "To create an endogenous type I IFN reporter, we chose the colorectal cancer cell line HCT116, which is highly efficient for CRISPR-based gene editing, and surveyed IFNα induction of canonical type I IFN target genes (IFIT1, IFIT2, IFIT3, IFI27, IRF7, OASL, RSAD2)." (PMID 38358346, 2024). "In this study, we identified IFIT1 and IFIT2 as genes down-regulated by Wnt signaling in colorectal cancer (CRC) cells, and clarified that inhibition of IFIT2 may play a role in the proliferation and anti-apoptotic properties of CRC cells." (PMID 29245969, 2017).
cervical carcinoma (4 papers, 2023 to 2025). A carcinoma arising from either the exocervical squamous epithelium or the endocervical glandular epithelium. "Notably, lower RSAD2 expression appeared to be linked to worse cervical cancer prognosis, while low IFIT1 expression was also associated with poorer survival, though its predictive power was not statistically significant (p > 0.05)." (PMID 40510586, 2025). "Although HPV infection upregulates IFIT1 expression in epithelial cells and T cells, its expression is markedly elevated in macrophages within cervical cancer tissues." (PMID 40510586, 2025). "As an ISG, IFIT1 has been implicated in the progression of HPV-related diseases, including HPV-associated head and neck squamous cell carcinoma (HNSCC), cervical cancer, and other HPV-related malignancies." (PMID 40510586, 2025). "Further analysis of IFIT1 expression suggests its complex role in immune regulation during cervical cancer progression." (PMID 40510586, 2025). "IFITs suppress RSV infection in human cervical carcinoma cells as shown by overexpression of IFIT1, IFIT2 or IFIT3 individually." (PMID 37515100, 2023). "However, in cervical cancer tissues IFIT1 expression was significantly upregulated, while RSAD2 showed no notable change." (PMID 40510586, 2025). "In the cervical cancer vs. normal tissue groups, RSAD2 and IFIT1 expression was significantly upregulated in macrophages and T cells, with additional expression observed in epithelial cells and proliferative cells." (PMID 40510586, 2025). "In contrast, in cervical cancer tissues, both RSAD2 and IFIT1 were markedly elevated in macrophages, and RSAD2 was significantly downregulated in fibroblasts." (PMID 40510586, 2025). "COL8A1 has been shown to promote non-small cell lung cancer progression by activating IFIT1/IFIT3-mediated EGFR signaling, while FABP5 can promote lymph node metastasis in cervical cancer by reprogramming fatty acid metabolism." (PMID 37795080, 2023). "Moreover, single-cell transcriptomic data analysis in this study revealed the dynamic expression patterns of RSAD2 and IFIT1 across different cell types, particularly during HPV infection and cervical cancer progression." (PMID 40510586, 2025). "Notably, single-cell transcriptomics revealed distinct RSAD2 and IFIT1 expression patterns in immune and epithelial cells during the progression from HPV infection to cervical cancer." (PMID 40510586, 2025). "ST analysis depicted the spatial overlap of IFIT1 and neutrophil biomarkers S100A9, and PDL1 on Cervical cancer (CESC), Glioblastoma Multiforme (GBM), Renal cell carcinoma (RCC), Breast invasive carcinoma (BRCA), and Bladder urothelial carcinoma (BLCA) cancer tissues." (PMID 38898490, 2024).
lung carcinoma (4 papers, 2020 to 2022). "Further, to explore the mechanisms of COL8A1 promoted lung cancer development, we found COL8A1 activated EGFR via upregulation of IFIT1 and IFIT3." (PMID 35280763, 2022).
Sepsis (4 papers, 2021 to 2025). Sepsis is defined as life-threatening organ dysfunction caused by a dysregulated host response to infection. "We observed an upregulation in the expression of IFI44, IFIH1, IFIT1, IFIT2, and RSAD2 in lung tissues from animals suffering from sepsis." (PMID 38239341, 2023). "Additionally, ZBP1, XAF1, IFI44L, SOCS1, and PARP14 were notably high in HighPANscore cells, aligning with our observations of upregulated expression of IFI44, IFIH1, IFIT1, IFIT2, and RSAD2 in lung tissues from sepsis-induced animal models." (PMID 38239341, 2023). "IFIT1 and IFIT2, although known for antiviral properties, were broadly expressed, suggesting their roles extend beyond viral defense to broader immune regulatory functions in sepsis." (PMID 38239341, 2023). "IFIT1 and IFIT2, known for their antiviral properties, exhibited broad expression across various cell types, indicating their involvement may transcend beyond viral defense mechanisms to broader immune regulatory roles within the context of sepsis." (PMID 38239341, 2023).
acute myeloid leukemia (3 papers, 2025 to 2026). Acute myeloid leukemia (AML) is a group of neoplasms arising from precursor cells committed to the myeloid cell-line differentiation. "These subnetworks included hub genes such as IFIT1, PSMB9, and HLA-B, which are known to be associated with immune evasion and drug resistance in acute myeloid leukemia." (PMID 42123467, 2026). "IFIT1, IFIT2, IFIT3, and IFIT5 are overexpressed in acute myeloid leukemia (AML) patients, with higher levels of IFIT2, IFIT3, and IFIT5 predicting poor prognosis." (PMID 41048997, 2025).
gastric cancer (3 papers, 2019 to 2025). A primary or metastatic malignant neoplasm involving the stomach. "The expression of PSMB8, IFIT2, and IFIT1 had prognostic value in gastric cancer at different stages." (PMID 31949544, 2019). "Upregulation of IFIT1 by TANs facilitated gastric cancer growth, migration and invasion." (PMID 40564154, 2025). "Upregulation of IFIT1 + TANs promote migration and invasion of gastric cancer (GC) cell lines (MKN45 and MKN74) and stimulates the growth of cell-derived xenograft models." (PMID 38898490, 2024).
glioblastoma (3 papers, 2022 to 2024). The most malignant astrocytic tumor (WHO grade IV). "In glioblastoma, IFIT1 is overexpressed in more than 80% of the cases, associated with a favorable outcome and long progression-free survival." (PMID 36077645, 2022).
glioma (3 papers, 2005 to 2023). A benign or malignant brain and spinal cord tumor that arises from glial cells (astrocytes, oligodendrocytes, ependymal cells). "In this study on glioma cells, the activation of numerous interferon-induced proteins (such as IFIT1, IFIT2, IFI27, IFITM1, IFITM2, and G1P2) lends support to this mechanism of pathogenicity." (PMID 15829208, 2005).
head and neck squamous cell carcinoma (3 papers, 2023 to 2025). A squamous cell carcinoma that arises from any of the following anatomic sites: lip and oral cavity, nasal cavity, paranasal sinuses, pharynx, larynx, and salivary glands. "Another study showed the overexpression of IFIT1 in head and neck squamous cell carcinoma, and there was correlation with bad prognosis and tumor-associated macrophage markers." (PMID 37817224, 2023). "The critical pro-oncogenic role of IFIT1 in cancers is illustrated in the example of oral squamous cell carcinoma (OSCC), an anatomical subset of broader head and neck squamous cell carcinomas (HNSCC)." (PMID 40564154, 2025).
leukemia (3 papers, 2023 to 2025). A malignant (clonal) hematologic disorder, involving hematopoietic stem cells and characterized by the presence of primitive or atypical myeloid or lymphoid cells in the bone marrow and the blood. "An important finding was the overexpression of the IFIT1 gene in BMMCs exposed to permethrin; overexpression of this gene has been detected in myelodysplastic syndromes before the development of leukemia, and is relevant for pre-B ALL." (PMID 37047231, 2023). "IFIT1 and IFIT3 have been implicated in proptosis induction in myeloma and leukemia cells." (PMID 41048997, 2025). "Additionally, a recent study reported that treatment with 20 μM clioquinol for 24 h induces pyroptosis of leukemia and myeloma cells via up-regulating IFIT1 and IFIT3." (PMID 39899169, 2025).
liver cancer (3 papers, 2023). An epithelial or non-epithelial malignant neoplasm that arises from the liver. "In a large multicenter study, patients with liver cancer were found to have low expression of IFIT1, IFIT2, and IFIT3." (PMID 38129382, 2023). "CAF (Cancer-associated fibroblast) secretes CXCL11 to induce liver cancer propagation and metastasis through circUBAP2, which is dramatically up-regulated upon CAF induction and functions as miR-4766 sponge to block inhibitory role of miR-4766 on IFIT1/IFTI3." (PMID 38933287, 2023). "Similarly with a recent study, IFIT1+ neutrophils showed distinct PDL1 expression in tumor microenvironment of liver cancer and might suggested immune suppression." (PMID 36709495, 2023). "Consequently, circUBAP2 maintains IFIT1/IFTI3 expression, which then induces downstream IL-17/IL-1β expression and secretion to promote propagation and metastasis of liver cancer." (PMID 38933287, 2023).
non-small cell lung carcinoma (3 papers, 2023 to 2024). A group of at least three distinct histological types of lung cancer, including non-small cell squamous cell carcinoma, adenocarcinoma, and large cell carcinoma. "We performed drug sensitivity analyses using the CellMiner database and found that AP-26113 (Brigatinib), a tyrosine kinase receptor inhibitor and antitumor drug, significantly promoted IFIT1 and IFIT2 expression for the treatment of some forms of advanced non-small cell lung carcinoma." (PMID 38737277, 2024).
astrocytoma (2 papers, 2013 to 2016). "IFIT1 (ISG56) expression increases in U373MG human astrocytoma cells." (PMID 27344170, 2016).
bladder cancer (2 papers, 2014 to 2023). "For example, it was reported that smoking induced a down-regulation of the interferon IFIT1 involved in the progression and invasiveness of bladder cancer." (PMID 25060307, 2014).
co-infection (2 papers, 2020 to 2025). "Collectively, these findings establish a robust molecular framework for understanding GV and HPV16 co-infection pathogenesis and highlight IFIT1 and RSAD2 as promising diagnostic biomarkers and therapeutic targets in HPV-related diseases." (PMID 40510586, 2025). "Our study also highlighted the pivotal role of hub gene RSAD2 and IFIT1 in the context of co-infection." (PMID 40510586, 2025). "To investigate the biological functions and signaling pathways co-regulated by the hub genes IFIT1 and RSAD2 during GV and HPV16 co-infection, we performed GSEA for each gene across both datasets." (PMID 40510586, 2025). "Single-gene GSEA analysis indicates that IFIT1 and RSAD2 regulate multiple biological processes during co-infection." (PMID 40510586, 2025). "The analysis revealed that the interferon-induced genes IFIT1 and RSAD2 play central roles in the pathological process of co-infection." (PMID 40510586, 2025). "Their mature forms, hsa-miR-34a-3p and hsa-miR-654-5p, can directly regulate the expression of IFIT1 and RSAD2, suggesting that they may be non-coding RNA molecules potentially influenced by co-infection and are worth further study." (PMID 40510586, 2025). "Our study identifies IFIT1 and RSAD2 as key regulators in GV and persistent HPV16 co-infection." (PMID 40510586, 2025). "Therefore, IFIT1 and RSAD2 are considered key regulatory factors during co-infection." (PMID 40510586, 2025).
colitis (2 papers, 2021 to 2022). Inflammation of the colon. "Importantly, inhibition of NF-κB, p-TBK1, and TBK1 at protein levels and transcription of Ifit-1, and Ifn-β were observed in the colon of cGAS deficient DSS-colitis mice." (PMID 34158863, 2021).
esophageal cancer (2 papers, 2023 to 2024). A primary or metastatic malignant neoplasm involving the esophagus. "High expression of IFIT1 was discovered in esophageal cancer cells, with possible correlations with prognosis." (PMID 37817224, 2023). "Interestingly, the proteomic study on esophageal cancer also noted that the immune response genes that they identified as differentially expressed (MX1, IDO1, IFIT1, and IFIT3) did not correspond to alterations in published genomic data." (PMID 39285636, 2024).
inflammatory bowel disease (2 papers, 2008 to 2025). A spectrum of small and large bowel inflammatory diseases of unknown etiology. "Inflammatory bowel disease was inversely associated with GATE scores for 5 interferon-stimulated genes—IFIT1, IFI44, HERC5, MX1, IFI44L—regulated by the same trans-expression quantitative trait locus, and with the GATE score for IFNL1." (PMID 40996888, 2025). "IFIT-1 (ISG56, P56) and IFIT-2 (ISG54, P54) are induced in response to type I and type II interferons, dsRNA, LPS, viral and bacterial infections and they are also found in several chronic diseases such as inflammatory bowel disease (IBD) or SLE." (PMID 19108715, 2008).
nasopharyngeal carcinoma (2 papers, 2020 to 2025). A carcinoma arising from the nasopharyngeal epithelium. "Sengupta dataset (41 patient samples) evaluated that expression of IFIT1 (p = 5.38 × 10−5), CCR4 (p = 0.046), and CCL4 (p = 2.79 × 10−8) genes were increased in nasopharyngeal carcinoma compared with normal nasopharynx." (PMID 32961854, 2020).
Obesity (2 papers, 2020 to 2024). Accumulation of substantial excess body fat. "Also, Ifit1 expression was higher in LCRs, which encodes for a component of interferon-induced protein complex that was previously linked to obesity-related inflammation." (PMID 33193103, 2020).
osteosarcoma (2 papers, 2022 to 2025). A usually aggressive malignant bone-forming mesenchymal neoplasm, predominantly affecting adolescents and young adults. "PARM1 was lowly expressed in osteosarcoma tissues, and low expression of IFIT1 predicted a poor prognosis for patients." (PMID 36950314, 2022). "The results showed that the expression of IFIT1 was high and the expression of PARM1 was low in the osteosarcoma cell line saos-2." (PMID 36950314, 2022). "Then we detected the protein levels of IFIT1 and PARM1 in the osteoblast cell line hfob 1.19 and the osteosarcoma cell line saos-2 by WB." (PMID 36950314, 2022).
ovarian carcinoma (2 papers, 2022). A malignant neoplasm originating from the surface ovarian epithelium. "IFIT1 (coding for interferon-induced protein with tetratricopeptide repeats 1) is another interferon response gene that was significantly induced on the transcript level after chemerin treatment in all ovarian cancer cell lines tested, with the strongest increase in OVCAR-3 cells." (PMID 36077645, 2022).
periodontitis (2 papers, 2022 to 2025). An acute or chronic inflammatory process that affects the tissues that surround and support the teeth. "It is known that the gene expressions of MX1 and IFIT1 in peripheral blood neutrophils of individuals with periodontitis are upregulated." (PMID 39669221, 2025).